RN7SKP190 (RN7SK pseudogene 190)
Gene: Miscellaneous RNA gene on chromosome 16 (82,192,505 to 82,192,790, reverse strand). Ensembl gene ENSG00000251888.
Homologues: Paralogues in human: RN7SKP189 (58% identical), 7SK (58% identical), RN7SKP217 (57% identical), RN7SKP162 (56% identical), RN7SKP170 (56% identical), RN7SKP127 (56% identical), RN7SKP149 (56% identical), RN7SKP174 (56% identical), RN7SKP185 (56% identical), RN7SKP187 (56% identical), RN7SKP77 (56% identical), RN7SKP240 (55% identical), and 284 more.